LTF (lactotransferrin)
Description:
Transferrins are iron binding transport proteins which can bind two Fe(3+) ions in association with the binding of an anion, usually bicarbonate. [Lactotransferrin]: Major iron-binding and multifunctional protein found in exocrine fluids such as breast milk and mucosal secretions. Has antimicrobial activity, which depends on the extracellular cation concentration. Antimicrobial properties include bacteriostasis, which is related to its ability to sequester free iron and thus inhibit microbial growth, as well as direct bactericidal properties leading to the release of lipopolysaccharides from the bacterial outer membrane. Can also prevent bacterial biofilm development in P.aeruginosa infection. Has weak antifungal activity against C.albicans. Has anabolic, differentiating and anti-apoptotic effects on osteoblasts and can also inhibit osteoclastogenesis, possibly playing a role in the regulation of bone growth. Promotes binding of species C adenoviruses to epithelial cells, promoting adenovirus infection. Can inhibit papillomavirus infections. Stimulates the TLR4 signaling pathway leading to NF-kappa-B activation and subsequent pro-inflammatory cytokine production while also interfering with the lipopolysaccharide (LPS)-stimulated TLR4 signaling. Inhibits neutrophil granulocyte migration to sites of apoptosis, when secreted by apoptotic cells. Stimulates VEGFA-mediated endothelial cell migration and proliferation. Binds heparin, chondroitin sulfate and possibly other glycosaminoglycans (GAGs). Also binds specifically to pneumococcal surface protein A (PspA), the lipid A portion of bacterial lipopolysaccharide (LPS), lysozyme and DNA. Lactoferricin binds to the bacterial surface and is crucial for the bactericidal functions. Has some antiviral activity against papillomavirus infection. N-terminal region shows strong antifungal activity against C.albicans. Contains two BBXB heparin-binding consensus sequences that appear to form the predominate functional GAG-binding site. [Kaliocin-1]: Has antimicrobial activity and is able to permeabilize different ions through liposomal membranes. [Lactoferroxin-A]: Has opioid antagonist activity. Shows preference for mu-receptor. [Lactoferroxin-B]: Has opioid antagonist activity. Shows higher degrees of preference for kappa-receptors than for mu-receptors. [Lactoferroxin-C]: Has opioid antagonist activity. Shows higher degrees of preference for kappa-receptors than for mu-receptors. The lactotransferrin transferrin-like domain 1 functions as a serine protease of the peptidase S60 family that cuts arginine rich regions. This function contributes to the antimicrobial activity. Shows a preferential cleavage at -Arg-Ser-Arg-Arg-|- and -Arg-Arg-Ser-Arg-|-, and of Z-Phe-Arg-|- aminomethylcoumarin sites. [Isoform DeltaLf]: Transcription factor with antiproliferative properties and ability to induce cell cycle arrest. Binds to the DeltaLf response element found in the SKP1, BAX, DCPS, and SELENOH promoters.
Synonyms: GIG12; LF; HLF2; HEL110
Tractability: Small molecule: a structure with a bound ligand is known; it has a high-quality binding pocket. Antibody: its Gene Ontology location is reachable by antibodies, with high confidence; UniProt places it where antibodies can reach, with medium confidence; UniProt predicts a signal peptide or a membrane-spanning region. PROTAC: UniProt records ubiquitination sites on it; ubiquitination databases record sites on it.
Target class: Enzyme; Hydrolase
Gene: Protein-coding gene on chromosome 3 (46,435,645 to 46,485,234, reverse strand). Ensembl gene ENSG00000012223.
Subcellular location: Secreted (Isoform 1); Cytoplasmic granule; Cytoplasm (Isoform DeltaLf); Nucleus
Pathways (Reactome):
Immune System: Antimicrobial peptides; Metal sequestration by antimicrobial proteins; Neutrophil degranulation
Disease: Mtb iron assimilation by chelation
Metabolism of proteins: Amyloid fiber formation
Gene Ontology:
Molecular function: cysteine-type endopeptidase inhibitor activity; heparin binding; iron ion binding; lipopolysaccharide binding; membrane destabilizing activity; protein binding; protein serine/threonine kinase activator activity; serine-type endopeptidase activity; peptidase activity
Biological process: antibacterial humoral response; antifungal humoral response; antimicrobial humoral immune response mediated by antimicrobial peptide; bone morphogenesis; defense response to Gram-negative bacterium; host-mediated suppression of viral genome replication; host-mediated suppression of viral proces; innate immune response in mucosa; killing of cells of another organism; negative regulation of lipopolysaccharide-mediated signaling pathway; negative regulation of single-species biofilm formation in or on host organism; positive regulation of canonical NF-kappaB signal transduction; positive regulation of chondrocyte proliferation; positive regulation of osteoblast differentiation; positive regulation of osteoblast proliferation; positive regulation of toll-like receptor 4 signaling pathway; regulation of cytokine production; regulation of tumor necrosis factor production; humoral immune response; iron ion transport; negative regulation of apoptotic process; negative regulation of osteoclast development; negative regulation of tumor necrosis factor (ligand) superfamily member 11 production; positive regulation of bone mineralization involved in bone maturation
Cellular component: cell surface; cytoplasm; extracellular exosome; extracellular region; nucleus; protein-containing complex; secretory granule; specific granule; early endosome; phagocytic vesicle lumen; plasma membrane; recycling endosome; specific granule lumen; tertiary granule lumen
Genetic constraint (gnomAD): Loss-of-function variants: 84 observed, 77.86 expected, observed/expected ratio (o/e) 1.08, 90% interval 0.9 to 1.29. The upper end of that interval is the gene's LOEUF score, 1.29, which puts it in group 5 of 6, group 1 being the genes least tolerant of losing a copy. Missense variants: 880 observed, 904.11 expected, observed/expected ratio (o/e) 0.97, 90% interval 0.92 to 1.03. Synonymous variants: 375 observed, 363.22 expected, observed/expected ratio (o/e) 1.03, 90% interval 0.95 to 1.12.
Homologues: Orthologues: chimpanzee LTF (98% identical), macaque LTF (90% identical), dog LTF (74% identical), rabbit LTF (74% identical), guinea pig LTF (72% identical), pig LTF (71% identical), mouse Ltf (71% identical), rat Ltf (62% identical), tropical clawed frog tf (48% identical), zebrafish tfa (39% identical). Paralogues in human: TF (60% identical), MELTF (41% identical), SRPRB (7% identical).
Diseases named in the same sentence as LTF in open-access papers:
LTF is named in the same sentence as 173 diseases in open-access papers, as found by Europe PMC text mining. Sharing a sentence is not in itself a finding about the gene and the disease. The quoted sentences say what the papers report.
Sepsis (20 papers, 2015 to 2026). Sepsis is defined as life-threatening organ dysfunction caused by a dysregulated host response to infection. "Similar with LCN2, LTF is also an iron-binding and multifunctional protein among the sepsis associated iron metabolism-related genes identified in this study." (PMID 36820206, 2023). "Comparative genomic analysis identifies LTF and MMP9 as key overlapping genes implicated in both pediatric sepsis and relapsed B-ALL." (PMID 41007866, 2025). "Based on the four diagnostic genes for sepsis and two diagnostic genes for relapsed B-ALL, LTF and MMP9 were identified as two key common genes." (PMID 41007866, 2025). "Then, four diagnostic genes of sepsis (LTF, MMP9, S100A9, and S100A8) and two diagnostic genes of relapsed B-ALL (LTF and MMP9) were screened by SVM-RFE, respectively." (PMID 41007866, 2025). "Within this study, elevated synovial levels of lactotransferrin (LTF) were identified within the sepsis group compared to the other pathologies." (PMID 31028944, 2019). "Lactotransferrin (LTF) abundance was increased in sepsis compared to all other groups and insulin-like growth factor-binding protein 6 (IGFBP6) abundance decreased in sepsis compared to other disease groups." (PMID 31028944, 2019). "This study suggests a critical role of LTF, LCN2, ELANE, MPO and CEACAM8 in sepsis and may provide potential diagnostic biomarkers and therapeutic targets for the treatment of sepsis." (PMID 38912048, 2024). "Notably, we identified five key genes (LTF, LCN2, ELANE, MPO, CEACAM8) associated with sepsis using the intersections of the top genes identified by cytoHubba and greenyellow module genes of the WGCNA." (PMID 38912048, 2024). "On the basis of the PCR test for the presence of pathogenicity genes (K88, LTF, STb) of translocated E. coli, these genes were not confirmed, and the total sepsis was induced by translocation of the non-pathogenic bacterium." (PMID 38255150, 2023). "The results indicated that the expression levels of LTF and MMP9 in the relapsed B-ALL with sepsis group were significantly higher than those in the control group (p < 0.001)." (PMID 41007866, 2025). "In septic foals, several genes, including PRDM16, WRAP53, LTF, and VLDLR, were activated to address inflammation or enhance survival rates in sepsis." (PMID 40867920, 2025). "Utilizing bioinformatic approaches, our study newly identified LTF and MMP9 as shared hub genes in pediatric sepsis and relapsed B-ALL." (PMID 41007866, 2025). "Differential gene expression analysis further demonstrated marked transcriptional upregulation of both LTF and MMP9 in the sepsis and relapsed B-ALL groups relative to the control group (p < 0.05), further supporting their potential as diagnostic biomarkers." (PMID 41007866, 2025). "In the present research, several genes linked to ER stress-response genes were identified, including PRDM16, WRAP53, LTF, and VLDLR, which exhibited increased expression in sepsis." (PMID 40867920, 2025). "A six-gene panel including EOMES, LTF, CSF1R, HLA-DRA, IRF8 and MPEG1 was discovered and validated with a high accuracy both in sepsis subjects and sepsis-induced ARDS subjects." (PMID 37443002, 2023). "Further ROC analysis suggested that the AUC of GCLM, LCN2, LTF, and CYP4V2 in diagnosis between severe forms and mild forms of sepsis were all >0.65." (PMID 36820206, 2023). "Three specific granule genes (OLFM4, LTF, and LCN2) showed <2-fold differences in SIRS vs. presurgical but >10-fold higher levels in sepsis vs. both SIRS and presurgical." (PMID 35844509, 2022). "LTF agonists are currently tested in phase I and III trials for sepsis and cancer." (PMID 41266628, 2025). "In conclusion, this study revealed the potential molecular mechanisms of key common genes with LTF and MMP9 in pediatric sepsis and relapsed B-ALL, which could provide novel insights for the clinical diagnosis of these two diseases." (PMID 41007866, 2025).
Sepsis (continued). "In addition, the expression levels of LTF, LCN, ELANE, MPO, and CEACAM8 were all up-regulated in the peripheral blood of sepsis patients than critical controls in the GSE131761 dataset, which is consistent with the previous findings." (PMID 38912048, 2024). "Subsequently, based on an external validation cohort from our hospital, qRT-PCR demonstrated significant up-regulation on LTF, LCN2, ELANE, MPO, and CEACAM8 in peripheral blood of sepsis patients versus controls, thus further enhancing the reliability of the findings." (PMID 38912048, 2024). "Additionally, when compared to sepsis shock, we found TPSO, GCLM, CYP1B1, LCN2, and LTF were up-regulated and the FTO and CYP4V2 were down-regulated in the sepsis (p < 0.05)." (PMID 36820206, 2023). "Differential analysis identified 6 proteins that were significantly upregulated in sepsis serum samples, including MMP9, lipocalin-2 (LCN2), serum amyloid A1 (SAA1), serum amyloid A2 (SAA2), paired-like homeobox 2B (PHOX2B), and lactoferrin (LTF) (|log2FC| > 1, P < 0.05)." (PMID 41306770, 2025). "In summary, our investigation conducted comprehensive bioinformatics analysis on two gene datasets (GSE28750 and GSE74224) and discerned LTF, LCN2, ELANE, MPO and CEACAM8 as key up-regulated genes in sepsis patients when compared with non-sepsis critically ill controls." (PMID 38912048, 2024).
mastitis (18 papers, 2009 to 2025). Inflammation of breast tissue during lactation or postpartum due to an obstructed duct or infection. "LTF is a multifunctional protein with antimicrobial properties that have an important defense role in innate immunity and has been associated with mastitis resistance in humans." (PMID 39009986, 2024). "The analysis of the effects of the TNF-α and LTF genes in relation to clinical mastitis showed strong associations between gene x parity interaction and MR, EM and DM of the disease." (PMID 23758855, 2013). "The finding that inflammation and involution of the mammary gland induces mammary expression of LF led to the suggestion that the LTF gene is a strong functional candidate for mastitis resistance or susceptibility." (PMID 19508288, 2009). "The LTF gene on BTA22 was found in mastitis expression experiments, association studies for milk phenotypes and association studies for mastitis resistance or susceptibility." (PMID 19508288, 2009). "In addition, previous studies showed that the polymorphisms present in the bovine LTF gene are closely connected to mastitis resistance or susceptibility." (PMID 31159303, 2019). "Furthermore, allele B of the LTF gene in the first parity was associated with a lower number while in the fifth one – with a higher number of days with mastitis." (PMID 23758855, 2013). "The objective of our study was to analyse 89 missense SNPs belonging to six genes (CXCR2, CXCL8, TLR4, BRCA1, LTF, BOLA-DRB3), which were found to be associated with genetic resistance or susceptibility to mastitis." (PMID 37174521, 2023). "In goats, the LTF gene for mastitis resistance was discovered to have an up-regulated expression profile in Damascus goats." (PMID 37756095, 2023). "We have analysed the missense SNPs belonging to six genes (CXCR2, CXCL8, TLR4, BRCA1, LTF, BOLA-DRB3) and identified one marker (rs110124025) in BOLA-DRB3 that was associated with frequency of mastitis and with the number of affected quarters." (PMID 37174521, 2023). "The protein lactotransferrin is a selective antibacterial milk protein that is involved in the mucosal protection of the mammary gland, and possibly protects against mastitis." (PMID 32005101, 2020). "We proposed tumor necrosis factor α (TNF-α), lactoferrin (LTF) and macrophage-expressed lysozyme (mLYZ) genes as potential DNA markers in the improvement of immunity to mastitis." (PMID 23758855, 2013). "Due to their biological functions, TNF-α, LTF and mLYZ genes have been proposed as potential DNA markers for immunity to mastitis." (PMID 23758855, 2013). "The mechanism of Glycyrrhizae Radix et Rhizoma in treating mastitis might be that the glycine it contains can regulate lactotransferrin level, enhance the body's immunity and exert anti-inflammatory effects." (PMID 30911319, 2019). "XS up-regulated expression of anti-bacterial genes (LTF and B2M), which may be beneficial to the host by preventing the incidence of mastitis." (PMID 30009039, 2018). "LTF gene expression in epithelial cells is 20 times higher than in leukocytes, indicating that LTF gene expression levels in ruminants may be a significant signal for mastitis resistance." (PMID 40542007, 2025). "Levels of IFN-γ, IL-4, TNF-α, MYD88, CCL5, TLR4, TLR9, LTF, PRLR, Keap1 and OXSR1 genes expression were significantly up-regulated in ewes affected with mastitis than resistant ones." (PMID 40542007, 2025). "Mastitis-affected ewes had considerably higher levels of IFN-γ, IL-4, TNF-α, MYD88, CCL5, TLR4, TLR9, LTF, and PRLR gene expression than resistant ones." (PMID 40542007, 2025). "Some of the genes differentially regulated during mastitis have been reported in multiple independent expression studies (e.g., CXCL8, CXCR1, LTF, TLR4)." (PMID 36759924, 2023). "Further studies are required to confirm the roles of LTF and TFL2 in mastitis in the Holstein breed in Vietnam." (PMID 35893772, 2022).
mastitis (continued). "The potential targets of these high-frequency CMM in treating mastitis were intercellular adhesion molecule 1 (ICAM-1), interleukin-6 (IL-6), lipopolysaccharide binding protein (LBP), and lactotransferrin." (PMID 30911319, 2019). "Lactoferrin (LTF) and Toll-like receptor 2 (TLR2) have been suggested as candidate genes for mastitis; however, their associations with the mastitis incidence and milk components have not been reported in Vietnamese Holstein cows." (PMID 35893772, 2022). "Conversely, mRNA expression of lactoferrin (LTF), which downregulates proinflammatory cytokines and prevents the release of inflammatory mediators, has not been changed among SCs from mastitis or no mastitis buffaloes." (PMID 39858163, 2025). "In the current investigation, qRT-PCR was used to measure the levels of antioxidant (CAT, GPX1, Keap1, OXSR1, ATOX1, GST, and Nrf2) and immune (IFN-γ, IL-4, TNF-α, MYD88, CCL5, TLR4, TLR9, LTF, and PRLR) genes in Barki ewes that were resistant and non-resistant to mastitis." (PMID 40542007, 2025).